NES (nestin)
Diseases named in the same sentence as NES in open-access papers (continued):
Sharing a sentence is not in itself a finding about the gene and the disease.
tumor (continued). "When the tumor spheres became adherent monolayers, one week after FBS-induced differentiation without growth factor supplementation in vitro, about 78–83% of the cells were still nestin positive." (PMID 18940013, 2008). "Nestin overexpression enhances the activity of the Wnt/β-catenin signal pathway, reducing levels of GSK-3β and promoting β-catenin nuclear localization, thereby improving tumor proliferation, invasion, and metastasis, and even reversing drug resistance, providing new strategies for cancer treatment." (PMID 40799240, 2025). "In addition, the stem cell marker nestin identified foci enriched with nestin+ cells that were distributed throughout the tumor, irrespective of the experimental group." (PMID 40083939, 2025). "Although we did not isolate tumour cells to confirm stem cell characteristics, previous human pituitary studies have demonstrated such findings in association with immunopositivity for markers CD133, SOX2 and Nestin." (PMID 38483762, 2024). "Subsequent multiplex immunofluorescence analysis of the tumor sections confirmed that Hsp70 was predominantly expressed in the regions (ii) and (iii) of VTs, colocalizing with the markers of tumor stem cells (i.e., cells expressing stemness markers SOX2, nestin, and Oct4)." (PMID 39015084, 2024). "On the other hand, when performing immunohistochemistry using Nestin as a marker to identify GBM cells, tumor cells (Nestin + ) presented strong reactive gliosis given the co-distribution of Vimentin (green) and GFAP (white) in the control, IKE and IKE + DHAA+Lpx conditions in the tumor area." (PMID 37752118, 2023). "However, this single marker was not sufficient to identify the CSC population across all tumors, and a series of additional cell markers, including Nestin and SOX2, have been confirmed to have differences in their ability to self-renew and initiate tumor formation." (PMID 36805592, 2023). "qRT-PCR analysis of xenograft tumor samples showed that the ADAMTS9-AS2–overexpressing group had higher levels of differentiation markers (Syn and Tau) and lower levels of MYCN and stem cell markers (Nestin and SOX2) compared with SK-N-Be2 cell xenograft vehicle groups." (PMID 37991019, 2023). "Furthermore, after radiotherapy, it is shown that only nestin-positive tumor cells collectively extended more TMs and survive while nestin-negative tumor cells tend to fail to respond in such way and get impaired." (PMID 35847909, 2022). "Finally, nestin was detected in SCLC tumor cells and tumor vessels in all clinical specimens." (PMID 34943921, 2021). "The NC group formed tumor tissues with more significant invasion and ill-defined margins and multiple protrusions toward the normal brain tissue, whereas the shCUX1 group formed tumor tissues with relatively smooth and clear edges with the normal brain tissue, revealed by HE and IHC of human Nestin." (PMID 33542188, 2021). "In order to investigate whether BET inhibition affects the tumor-initiating ability of EPN SC cultures, we assessed the expression of previously defined neural cancer SC markers (PROM1, NES and SOX2) and of the astrocytic marker GFAP in the cells treated with OTX015." (PMID 33668642, 2021). "Indeed, we encountered a case of an SCLC patient who showed nestin-negative tumor cells at initial diagnosis that became positive after first-line chemotherapy (not shown)." (PMID 32903755, 2020). "The administration of ODZ10117 dramatically decreased the tumor population and the levels of active STAT3, CSC markers such as NESTIN and SOX2, and MES-associated genes FN and ITGAV without significantly affecting the body weight compared to the vehicle-treated control group." (PMID 32183406, 2020). "Nestin contributes to activation of the EMT pathway by regulating the Wnt/β-catenin pathway and may therefore play a role not only in the regulation of mitosis, but in tumor invasiveness." (PMID 30819139, 2019).
tumor (continued). "However, the pathological assessment of Nestin expression in human samples is performed on all the cells within the tumor mass (for obvious reasons, since human tumor cells do not express a reporter gene)." (PMID 31511246, 2019). "Therefore, we propose that GFAP/CD90+/CD44+ EPN cells correlate with the expression of CD133, nestin, CXCR4 and SSEA-3, which could act as markers of enrichment for tumor-initiating cells." (PMID 29774098, 2018). "In the primary cell culture of the tumor tissues obtained from the tumor periphery of four GBM patients, we obtained two SFCs (SFC-1 and SFC-2), both of which expressed much higher amounts of mRNA of neural stem cell markers CD133, Nestin, and CD44 than each PCs." (PMID 30210550, 2018). "Nestin appeared to be showing a different pattern with reduced levels of expression (none in many samples) in the invasive areas but with elevated levels in tumour core and rim areas but again this did not achieve significance (p = 0.212)." (PMID 29156557, 2017). "However, when fluorescent probes were used, the intense auto-fluorescence of this type of tumor (data not shown) hindered confident identification of cells stained for nestin." (PMID 26018884, 2015). "Since the potential of tumor formation is inversely correlated to the degree of differentiation, we selected cells after 6 passages for transplantation because nearly all hNSCs were Nestin-positive and Oct4-/Nanog-negative at this time point." (PMID 26541394, 2015). "Similarly, up-regulation of stemness-related genes (ALDH1A1, Nanog, Nestin, Bmi1, and Oct4) was observed in HCC87/gef cells, implying that these gefitinib-resistant cells contained a larger population of tumor-initiating cells." (PMID 25871388, 2015). "Taken together with other reports describing a role for CXCR4 in the regulation of neural stem cell function our data showing that POL5551 reduced the numbers of nestin positive perivascular cells, led us to hypothesize that POL5551 might have direct effects on tumor stem cells." (PMID 25238146, 2014). "In addition, CD133, CD90, CD44, and Nestin co-expression may explain the tumorigenic potential of these cells, since Nestin and CD44 are also known as regulators of migration, invasion and tumor growth." (PMID 24432012, 2014). "Interestingly, the primary tumor of BC-P007 xenograft at the site of injection expressed collagen type II (50% moderate staining, data not shown), but not nestin, βIII-tublin and GFAP." (PMID 24670249, 2014). "To examine whether these CD34− cells were tumor cells, we double-stained CD34 and nestin." (PMID 23536763, 2013). "When the tumor cells were epithelioid, there was weak or even no expression of nestin." (PMID 23420140, 2013). "To investigate whether these individual flavonolignans inhibited the xenograft growth by suppressing tumor angiogenesis, we stained the tumor section with CD31 (a biomarker for matured microvessels) and nestin (a biomarker for immature and newly formed microvessels)." (PMID 22514647, 2012). "Mela1 spheroid cells also expressed CD146, CD166, nestin, but not integrin αvβ3, which could be due to the tumor progression state of Mela1 cells given that αvβ3 is reported as mainly expressed in metastatic regions." (PMID 21526207, 2011). "Within a single sphere grown from one CD133+ GSC, the cells expressed markers of different neural lineages at constant proportions; most of the tumor cells did not differentiate terminally and often co-expressed differentiation markers with the stem/progenitor cell marker nestin." (PMID 18940013, 2008). "Whereas neither Nestin-cre::Smarcb1fl/+ nor Olig1-cre::Smarcb1fl/+ mouse strains showed any pathological phenotype (Ca’), hGFAP-cre::Smarcb1fl/+ and Math1-cre::Smarcb1fl/+ mice gave rise to different tumor entities with a tumor penetrance of 11% and 4%, respectively." (PMID 35318328, 2022). "Of note, Nestin could not be detected in endothelial cells of newly formed tumor blood vessels." (PMID 25019063, 2014).
tumor (continued). "Similarly, Nestin expression was absent in tumor cells except for 2 cases." (PMID 23424657, 2013). "By contrast, Dlk1+ cells were detected in all tumours irrespective of time of onset (n = 15) but retained their hepatocytic morphology and were spatially distinct from NOTCH1/nestin+ regions, where Dlk1+ cells tended to exhibit lower NRAS expression." (PMID 39112713, 2024). "By immunohistochemistry, the tumour strongly expressed S100 and GFAP in addition to intense nestin positivity, while OLIG2 was negative in the perivascular tumour cells." (PMID 37362245, 2023). "Under the serum‐free microfluidic tumor‐on‐chip model, GB3‐RFP cells expressed Nestin, the neural progenitor cell marker, but not GFAP, or AQP4, suggesting that GB3‐RFP cells retained their stem properties during invasion (Figure 3biii)." (PMID 35619544, 2022). "While not significant, higher levels of the stem cell markers Nestin, Vimentin and SSEA1 were also seen in the Lrig1 KO tumours." (PMID 36420140, 2022). "Immunohistochemical analysis showed tumor cells positive for BMP-2, osteonectin, osteocalcin, AE1/AE3, TGF-β1, Gli2, Smad2/3, and CDX2 and negative for nestin, CD56, and CK7." (PMID 33388078, 2021). "Nestin, KLF4, ALDH1, EPCAM as well as ABCG2 expression was incongruous, with no clear relation to the four different parental tumor groups." (PMID 33800955, 2021). "Our data also support the notion that there is a set proportion of cells expressing DCX/NES/OLIG2, regardless of treatment, guided by tumour plasticity." (PMID 34948016, 2021). "The tumor cells were robustly and diffusely positive for Trk, S100-protein, CD34, and nestin, but negative for CD56, SMA, desmin, myogenin, STAT6, EMA, CK, CD1a, CD21, CD35, CD43, WT-1(c-terminal), MelanA, HMB45, BRAF, and ALK." (PMID 32957984, 2020). "Bcan-Ntrk1-induced tumors showed elevated percentage of Ki67-positive cells, were positive for OLIG2 and NESTIN, negative for the neuronal marker NeuN and GFAP-positive cells were almost exclusively detected at the normal/tumor border." (PMID 29654229, 2018). "Cells positive for Nestin, CD133, GFAP, BIIIT, SSEA4, and Olig2 had a tumor-dependent pattern of expression, which did not have a dichotomous association with grade." (PMID 29849507, 2018). "Few FTH-positive tumor cells co-expressed CD133, while no co-expression between FTH and nestin was observed." (PMID 28837569, 2017). "To this regard, we demonstrated the expression of phosphorylated mitogen-activated protein kinases and of the stem cell marker nestin in the peritumoral tissue of GBM, even in the absence of tumor cells." (PMID 27705944, 2016). "In agreement with the results of immunohistochemical analysis, flow cytometry analysis also revealed that an average of 12% (range 2–19%) of fresh (not cultured) tumor cells expressed IL-17R and 75% of IL-17R+ cells co-expressed GSC markers CD133 and Nestin." (PMID 26755664, 2016). "We observed that the expression of 10 of 12 CSC-related markers (CD90, ALDH1, CK7, CK19, OCT4, SOX2, vimentin, nestin, CD13 and EpCam) was not significantly different between the tumor tissues and peritumoral tissues." (PMID 27329727, 2016). "The obtained tumor was negative for GFAP and showed high Nestin expression and weak expression of β3 Tubulin, and a high proliferation rate as indicated by positive Ki67 staining." (PMID 25275602, 2014). "While our results suggest that nestin contributes to the proliferation and apoptosis in ESCC cells, other aspects of metastasis, such as angiogenesis, lymphangiogenesis and tumor metabolism, were not directly examined." (PMID 24966803, 2014). "When evaluated by immunohistochemistry, the tumor tissue expressed mesenchymal cell makers Vim, CK, and CD99, neural cell markers NF and NES, but was negative for epithelial markers EMA and Des." (PMID 24339974, 2013).
tumor (continued). "Evaluation of cancer stem cell-associated markers showed consistent expression of CD44, Nanog, Oct3/4, and Sox2 in the original tumours and cell lines, while CD133, Nestin, and Trop2 were present in the tumours but absent in vitro, indicating selective loss of specific stem-like populations." (PMID 41828941, 2026). "Similarly, in GH-secreting tumor tissues, no co-expression of GH with SOX2, OCT4, or Nestin was observed." (PMID 31708878, 2019). "Indeed, all 3 populations were ALDH+ and formed serial spheroids but expressed different combinations of stem cell markers (CD133, CD105, CD146, CD29, OCT4, NANOG, and Nestin) and the non-CSC tumor marker E-cadherin." (PMID 27293448, 2016). "On the other hand, the expression of CD166, CD133, CD44, A2B5, CD56, NGFR and DCX seemed to be higher in UA cells, but also not statistically significant, while the expression of CD9, Nestin, GFAP, CD24, PDGFRb, PDGFRa, MAP2, TUBIII, S100 were consistently high in both UA and tumor core samples and." (PMID 27605047, 2016). "SiRNA knockdown of SOD2 expression significantly reduced mean TrkAIII SH-SY5Y tumour spheroid volume but, unlike GW441756, did not reduce Nanog, Nestin, SOX2 or CD117 expression in tumor spheroids, implicating SOD2 in the promotion of SH-SY5Y tumour spheroid growth and survival but not staminality." (PMID 24736663, 2014). "Using xenograft tumors growing on bone-marrow (BM) chimera of C57Bl/6 wildtype and Nestin-GFP transgenic mice, we show for first time that Nestin(+) cells inducing the maturation of tumor vessels do not originate from the BM but presumably reside within the adventitia of adult blood vessels." (PMID 25019063, 2014).
cancer (252 papers, 2006 to 2026). A tumor composed of atypical neoplastic, often pleomorphic cells that invade other tissues. "Despite these associations, the molecular mechanisms underlying nestin’s role in cancer cell malignancy remain largely unclear, leaving a critical gap in understanding its contribution to cancer progression." (PMID 39851565, 2025). "Based on the meta-analysis of fourteen cohort studies, it was found that higher levels of nestin in cancer tissue are associated with poorer survival, such as OS and DFS, in patients with DTCs." (PMID 37485559, 2023). "Nestin is a type VI intermediate filament (IF) protein that has been implicated in progenitor cell functions, development of nerve systems, cancer pathogenesis, and smooth muscle cell migration." (PMID 37316833, 2023). "Several cancers have been associated with poor prognoses based on nestin, a confirmed marker of cancer stem cells." (PMID 37485559, 2023). "In cancer presentation and progression, nestin expression has been associated with several processes, including cell proliferation, metastasis, and angiogenesis." (PMID 37509714, 2023). "Nestin undergoes phosphorylation at Thr-315 in cancer cells and is associated with cell proliferation." (PMID 37316833, 2023). "Eleven studies reported the association between the level of nestin expression in cancer tissue and OS in patients with DTCs." (PMID 37485559, 2023). "Taken together, these results suggested that higher nestin in cancer tissue is associated with poor survival of DTCs, particularly for patients with gastric and LCs." (PMID 37485559, 2023). "Nestin is a type VI IF protein that has been implicated in progenitor cell functions, neuronal development, cancer pathobiology, and smooth muscle cell migration." (PMID 37316833, 2023). "Nestin is a class VI IF protein that is implicated in the proliferation/regeneration of neurons, cancer cells, and skeletal muscle." (PMID 36231009, 2022). "Previous reports have clarified the underlying molecular mechanisms of Nestin in cancer development." (PMID 34837964, 2021). "Nestin is considered a marker of stemness and has been linked to the proliferation of cancer stem cells and poor prognosis." (PMID 33584136, 2021). "In the presentation and progression of cancer, nestin expression has been associated with several processes, including cell proliferation, angiogenesis, and metastasis." (PMID 34943921, 2021). "In patients with triple-negative breast cancer, increased nestin expression was associated with upregulation of cancer stem cell markers, MMP2, -9, VEGF, and other proteins associated with proliferation by enhancing the Wnt/β-catenin activation." (PMID 33171868, 2020). "Associations between nestin expression and efficacy of chemotherapy have previously been reported for other cancer types, and these results are in line with those findings." (PMID 32903755, 2020). "In this review, we draw from recent studies focused on three IF proteins most associated with cancer (keratins, vimentin, and nestin) to highlight how several “hallmarks of cancer” described by Hanahan and Weinberg are impacted by IF proteins." (PMID 31126068, 2019). "Recent reports showed that high expression of nestin correlated with malignant characteristics in several carcinomas and suggested that elevated content of nestin in cancer cells was linked to greater aggressiveness and poor prognosis." (PMID 29029411, 2017). "The association between DLL4 expression level and the cancer stem cell related protein Nestin was also analyzed." (PMID 27891816, 2017). "In the present meta-analysis, we summarized the associations of Nestin with clinicopathological features and OS in a single type of cancer, NSCLC." (PMID 27150062, 2016). "This analysis provided evidence of an association between positive/high nestin and median/advanced cancer stage in different cancers, demonstrating a significant main effect of positive/high nestin versus negative/low nestin." (PMID 26015397, 2015).